ALKBH5 (alkB homolog 5, RNA demethylase)
Diseases named in the same sentence as ALKBH5 in open-access papers (continued):
Sharing a sentence is not in itself a finding about the gene and the disease.
neuroblastoma (7 papers, 2022 to 2025). Neuroblastoma (NB) is the most common solid, extracranial childhood tumor. "In a Chinese population, the ALKBH5 variant rs8400 was found to be associated with an increased neuroblastoma risk." (PMID 40361322, 2025). "More studies are required to confirm this negative result and reveal the relationship between gene polymorphisms of the m6A modifier ALKBH5 and neuroblastoma." (PMID 38946930, 2023). "Notably, it has been identified that the m6A demethylase‐encoding gene ALKBH5 has a polymorphism called rs8400 G > A, increasing susceptibility to neuroblastoma and shedding light on associated mechanisms." (PMID 39039912, 2024). "The ALKBH5 gene, linked to NB susceptibility, has been reported to inhibit NB progression by reducing YAP expression and activity, and to promote malignant progression by inhibiting SPP1 expression in high‐grade neuroblastoma, where it is often amplified and upregulated." (PMID 38925618, 2024). "To explore the effects of METTL3 and ALKBH5 on ADAMTS9-AS2 upregulation in neuroblastoma cells, we knocked down the expression of METTL3 in SK-N-SH cells and knocked down ALKBH5 in SK-N-Be2 cells." (PMID 37991019, 2023). "The endogenous expressions of METTL3 and ALKBH5 of the neuroblastoma cell lines regulated the m6A modification in ADAMTS9-AS2, thus affecting its RNA stability and its downstream MYCN expression." (PMID 37991019, 2023). "The endogenous expressions of METTL3 and ALKBH5 in the neuroblastoma cell lines were analyzed; the results showed that ALKBH5 expression was lowest and that METTL3 expression was highest in the SK-N-SH cells." (PMID 37991019, 2023).
acute kidney injury (6 papers, 2023 to 2025). Sudden and sustained deterioration of the kidney function characterized by decreased glomerular filtration rate, increased serum creatinine or oliguria. "IOX1, the clinical pharmacological inhibitors of ALKBH5, competitively inhibits 2OG binding and suppresses ALKBH5, which demonstrates protective effects against acute kidney injury and sevoflurane-induced neuronal damage in the hippocampus." (PMID 40831573, 2025). "It was reported that IOX1, a broad-spectrum inhibitor of 2-OG oxygenases, suppressed ALKBH5 expression by competing with 2-OG, which prevented acute kidney injury (AKI) and age-related macular degeneration (AMD)." (PMID 40001461, 2025). "Subsequently, it was demonstrated that the ALKBH5 inhibitor IOX1 protects against ischemia/reperfusion-induced acute kidney injury (AKI)." (PMID 39192357, 2024). "However, a contrary trend was observed in ischaemia/reperfusion (I/R)‐induced acute kidney injury and fibrosis, where a decrease in ALKBH5 was found to protect against the I/R‐induced kidney injury and fibrosis by regulating the inflammatory process." (PMID 39233335, 2024). "Elevated levels of total renal M6A were detected in cisplatin-induced acute kidney injury (cis-AKI) in mice, accompanied by alterations in METTL3, Mettl14, WTAP, FTO and AlKBH5." (PMID 37865763, 2023).
cardiac hypertrophy (6 papers, 2022 to 2025). "A recent study showed the decreased m6A level in Ang II-induced H9C2 cells hypertrophy, which is caused by the upregulation of ALKBH5, indicating the potential function of ALKBH5 during the cardiac hypertrophy." (PMID 39294131, 2024). "Surprisingly, both the protein and mRNA levels of ALKBH5 were upregulated in HFD-induced cardiac hypertrophy, while Fat mass and obesity-associated protein (FTO), the first reported m6A demethylase in eukaryotic cells, was also upregulated but not as high as ALKBH5." (PMID 39294131, 2024). "Conversely, suppressing METTL3-mediated m6A modification inhibits cardiac hypertrophy to some extent, and this phenomenon is correlated with ALKBH5." (PMID 40290189, 2025). "ALKBH5 plays a role in RNA demethylation, and its effects on cardiac hypertrophy are both beneficial and detrimental." (PMID 40290189, 2025). "To define the potential role of ALKBH5 in pathological cardiac hypertrophy, we firstly analyzed the available data from human RNA-sequencing (RNA-seq) (GSE116250), namely transcriptomic data of 58 samples from human left ventricle tissue." (PMID 39294131, 2024). "We further found that the expression of circPan3 in cardiac hypertrophy is affected by Alkylated DNA repair protein alkB homolog 5 (ALKBH5) mediated N6-methylation." (PMID 38172650, 2024). "We revealed the role of Tan IIA in galectin-3 and m6A modification as well as the role of ALKBH5 in cardiac hypertrophy." (PMID 35191812, 2022). "Tan IIA suppressed m6A modification of galectin-3 via downregulating ALKBH5, which suppressed the development of cardiac hypertrophy." (PMID 35191812, 2022). "Moreover, the mRNA level of Alkbh5 gene was also upregulated in TAC-induced cardiac hypertrophy, which is consistent with the transcriptional results from humans." (PMID 39294131, 2024). "Harnessing ALKBH5 in cardiomyocytes might be an effective approach to break the progression of pathological cardiac hypertrophy." (PMID 39294131, 2024). "Rescue experiments were performed to elucidate the role of ALKBH5 in cardiac hypertrophy." (PMID 35191812, 2022). "To investigate whether ALKBH5 regulates cardiomyocyte hypertrophy so as to result in cardiac hypertrophy in diverse pathological conditions, we examined ALKBH5 expressions in cardiomyocytes under classical hypertrophic agonists treatments, such as PE and isoprenaline (ISO)." (PMID 39294131, 2024). "CircPan3 inhibits cardiac hypertrophy by targeting the miR-320-3p/HSP20 axis and is regulated by ALKBH5-mediated N6-methylation." (PMID 38172650, 2024). "We revealed that the mRNA and protein levels of ALKBH5 were upregulated in both phenylephrine (PE)-induced cardiomyocyte hypertrophic responses in vitro and TAC/high fat diet (HFD)-induced cardiac hypertrophy in vivo." (PMID 39294131, 2024). "Thus, to explore the downstream regulator of ALKBH5 in cardiomyocyte hypertrophy, the JAK2/STAT3 pathway piqued our interest due to its pivotal role in cardiac hypertrophy." (PMID 39294131, 2024). "ALKBH5 showed upregulation in both phenylephrine (PE)-induced cardiomyocyte hypertrophic responses in vitro and transverse aortic constriction (TAC)/high fat diet (HFD)-induced pathological cardiac hypertrophy in vivo." (PMID 39294131, 2024). "Additionally, ALKBH5 mediates the demethylation of STAT3 and regulates the expression of inflammatory factors (such as IL-6 and TNF-α) by activating the JAK2/STAT3 signaling pathway, thereby affecting the progression of cardiac hypertrophy." (PMID 40290189, 2025).
esophageal cancer (6 papers, 2021 to 2024). A primary or metastatic malignant neoplasm involving the esophagus. "Studies have found that the m6A regulators in esophageal cancer all play a cancer-promoting role, except for ALKBH5." (PMID 35945641, 2022). "The results of univariate cox regression revealed that ALKBH5 (P = 0.001) was a protective gene for esophageal cancer." (PMID 34395102, 2021). "ALKBH5 plays dual roles in promoting and suppressing tumor growth in esophageal cancer." (PMID 35945641, 2022). "However, a study showed that ALKBH5 inhibits the malignant behavior of esophageal cancer by indirectly regulating the Hippo signaling pathway." (PMID 35945641, 2022). "Knocking down ALKBH5 upregulates m6A level on CDKN1A(p21) mRNA, increases the stability of p21 mRNA, and promotes the proliferation of esophageal cancer cells by regulating cell cycle progression." (PMID 35945641, 2022). "The results showed that the low expression of ALKBH5 and the high expression of HNRNPC or WTAP were the best predictors for poor OS rates in esophageal cancer patients." (PMID 34395102, 2021). "Then, ELISA result showed that METTL3 and METTL14 were highly expressed in esophageal cancer, whereas FTO and ALKBH5 expressed lowly in esophageal cancer." (PMID 33596916, 2021). "However, during the development of esophageal cancer, FTO has an antagonistic effect on the expression of METTL14, and this effect is related to the ratio of FTO to ALKBH5." (PMID 38491196, 2024). "Our research showed that the independent expression of FTO was not significantly correlated with the prognosis of esophageal cancer patients, which is different from the mechanism of ALKBH5." (PMID 38491196, 2024). "A previous study showed that ALKBH5 knockdown increased m6A modification and mRNA stability of CDKN1A, which subsequently increased p21 protein expression and acted as a tumor suppressor in esophageal cancer." (PMID 35318440, 2022). "ALKBH5 functions in esophageal cancer cells (ESCC), and its overexpression results in the inhibition of proliferation, migration, and invasion by arresting cells in the G1 phase; however, demethylated mRNA of ALKBH5 and related signaling pathways in ESCC are unclear." (PMID 37965577, 2023).
hepatoblastoma (6 papers, 2021 to 2024). Hepatoblastoma (HB) is a malignant hepatic tumor and is the most common pediatric liver cancer. "We have previously shown that several RNA m6A-mediated genes (i.e., METTL3, METTL14, WTAP, YTHD1, YTHDC1, and ALKBH5) are associated with hepatoblastoma susceptibility." (PMID 35986847, 2022). "In summary, our study provides some clues of a potential modulating effect of ALKBH5 gene SNPs on hepatoblastoma risk." (PMID 33790968, 2021). "We further attempted to interpret the possible mechanism of ALKBH5 gene rs8400G > A-mediated hepatoblastoma risk." (PMID 33790968, 2021). "In all, our investigation presents evidence of a weak impact of ALKBH5 gene polymorphisms on hepatoblastoma risk, using the largest hepatoblastoma sample size." (PMID 33790968, 2021). "Here, we carried out by far the largest study to determine whether ALKBH5 gene SNPs could predispose to hepatoblastoma risk in Chinese children." (PMID 33790968, 2021). "Our findings support the concept that genetic variation of ALKBH5 gene may be implicated in the pathogenesis of hepatoblastoma." (PMID 33790968, 2021). "This study aims to test the hypothesis that hepatoblastoma risk may be modulated by genetic polymorphisms in ALKBH5 gene based on genotyped data from samples of 328 cases and 1476 controls enrolled from eight hospitals in China." (PMID 33790968, 2021). "Similar studies detected the association between YTHDC1 and ALKBH5 polymorphism and hepatoblastoma." (PMID 34367972, 2021). "We used TaqMan assay to genotype ALKBH5 gene single nucleotide polymorphisms (SNPs) rs1378602G > A and rs8400G > A. We calculated the odds ratios (ORs) and P values using logistic regression models to estimate the association between hepatoblastoma risk and ALKBH5 gene SNPs." (PMID 33790968, 2021). "Our group has previously reported that many genetic variants of genes encoding RNA m6A and m7G methyltransferase, demethylase, and m6A-reading proteins confer hepatoblastoma susceptibility, including METTL3, METTL4, AlkB homolog 5 (ALKBH5), FTO, YTHDC1, YTHDF1, WTAP, WDR4, and METTL1." (PMID 37531210, 2023). "A better understanding of the role of ALKBH5 gene SNPs in the pathogenesis of hepatoblastoma might lead to new methods for the prevention and treatment of this disease." (PMID 33790968, 2021). "Given the important role of ALKBH5 gene in cancer as well as the lack of research on this gene in hepatoblastoma, we performed the current study to investigate the association between ALKBH5 gene SNPs and the risk of hepatoblastoma." (PMID 33790968, 2021).
ischemic heart disease (6 papers, 2020 to 2024). "This suggests that METTL3 behaves as a negative regulator of autophagy in ischemic heart diseases, while ALKBH5 functions oppositely." (PMID 38988324, 2024). "Together, our study reveals a critical role of ALKBH5-medicated m6A on CM apoptosis, supplying an important regulating effect of m6A methylation in ischemic heart disease." (PMID 37193033, 2023).
lymph node metastasis (6 papers, 2021 to 2025). "Statistical analysis of clinical characteristics displayed that elevated expression of ALKBH5 was positively associated with a good prognosis and suppressed distant tumor metastasis and lymph node metastasis in patients." (PMID 35114989, 2022). "Patients with castration-resistant prostate cancer (CRPC) with bone metastasis also showed less ALKBH5 downregulation compared to patients with CRPC with lymph node metastasis." (PMID 36133437, 2022). "Decreased expression of ALKBH5 was detected in GC samples, and it was correlated with clinical tumor distal metastasis and lymph node metastasis." (PMID 35114989, 2022). "Conversely, the expression levels of ALKBH5, ALKBH8 and FTO were lower than those in normal tissues at any stage of lymph node metastasis." (PMID 34150745, 2021). "The expression of METTL3, METTL14, WTAP, YTHDC2, YTHDF1, and YTHDF2 was remarkably higher in CRPC with lymph node metastasis than in CRPC with bone metastasis, whereas ALKBH5, FTO, and YTHDF3 were substantially decreased in CRPC with lymph node metastasis." (PMID 33403026, 2021). "Furthermore, ALKBH5 gradually decreased with increasing tumor grade in HPSCC tissue and was negatively correlated with the maximum tumor diameter and lymph node metastasis." (PMID 37612282, 2023).
multiple myeloma (6 papers, 2022 to 2025). "ALKBH5 deficiency in myeloma cells significantly enhanced the SAV1 mRNA methylation level and therefore regulated its stability and expression, led to YAP phosphorylation and finally resulted in YAP deactivation." (PMID 35414790, 2022). "Our previous research has demonstrated that ALKBH5 promoted stem cell phenotype and myeloma tumorigenicity through demethylating the SAV1 mRNA of the HIPPO pathway, emphasizing the demethylation activity of ALKBH5 in MM." (PMID 38145297, 2024). "In contrast, ALKBH5 is upregulated in myeloma, and its inhibition represses the myeloma cell proliferation, invasion, and migration ability, while it promotes apoptosis." (PMID 37063421, 2023). "Mechanistic studies showed that ALKBH5 exerted tumorigenic effects in myeloma in an m6A-dependent manner, and TNF receptor-associated factor 1 (TRAF1) was a critical target of ALKBH5." (PMID 34759347, 2022). "Knockdown of the ALKBH5 gene inhibited myeloma cell proliferation, neovascularization, invasion and migration ability and promoted apoptosis both in vitro and in vivo." (PMID 35414790, 2022). "Downregulation of ALKBH5 inhibited myeloma cell proliferation, neovascularization, invasion and migration ability, and promoted the apoptosis in vivo and in vitro." (PMID 35414790, 2022). "Gene Expression Omnibus (GEO) dataset analysis demonstrated that the elevated ALKBH5 expression was correlated with myeloma disease progression from normal to smoldering myeloma (SMM) and from MM to plasma cell leukemia (PCL)." (PMID 34759347, 2022). "Taken together, our MM cell xenograft models and GSEA of myeloma patient data sets supported the role of ALKBH5 in the malignant progression of myeloma in vivo." (PMID 34759347, 2022). "Quantitative PCR (qPCR) analyses also showed that ALKBH5 mRNA levels were significantly higher in purified primary myeloma cells and established human myeloma cell lines (HMCLs) compared with peripheral blood mononuclear cells (PBMCs) from healthy donors." (PMID 34759347, 2022). "In the future, we need to address the function of ALKBH5 in purified myeloma stem cells which help its application as effective cancer stem cell targeted therapeutics." (PMID 35414790, 2022). "In this study, we found that ALKBH5 was highly expressed in both primary CD138+ plasma cells isolated from multiple myeloma (MM) patients and MM cell lines." (PMID 35414790, 2022). "Consistently, the expression of ALKBH5 in myeloma cell lines, including RPMI8226, ARH-77, NCI-H929 and U266 cells, was more abundant than that in the normal controls (P<0.05)." (PMID 35414790, 2022). "Using various HMCLs and xenograft models, we demonstrated that ALKBH5 and its demethylation activity were required for myeloma cell growth and survival." (PMID 34759347, 2022). "More importantly, we found that ALKBH5 deficiency in MM cells enhanced the RNA methylation of the HIPPO pathway-initiating protein SAV1, suppressed the activation of the HIPPO pathway, and ultimately reduced the proportion of myeloma stem cells." (PMID 35414790, 2022). "It showed that knockdown of ALKBH5 could inhibit the VEGF secretion ability in myeloma cells (P< 0.001)." (PMID 35414790, 2022). "Our study suggested a novel epigenetically interaction of N6-methyladenosine (m6A) methylation, lncRNA SNHG15, and histone SETD2/H3K36me3 modifications in myeloma progression, indicating that ALKBH5 and lncRNA SNHG15 could serve as potential novel therapeutic targets for MM treatment." (PMID 38145297, 2024). "Thus, we focused on exploring the role of ALKBH5 in myeloma tumorigenesis." (PMID 34759347, 2022). "According to the Arkansas myeloma cohort (GEO accession number GSE4581), the elevated expression of two m6A demethylases (ALKBH5 and FTO) was correlated with poor patient survival." (PMID 34759347, 2022).
multiple myeloma (continued). "Moreover, the novel chromatin-regulatory mechanism of lncRNA by interacting with epigenetic modifiers including m6A demethylase ALKBH5 and H3K36me3 methyltransferase SETD2 in myeloma progression elucidated intricate mechanism of tumor pathogenesis." (PMID 38145297, 2024). "Inhibiting ALKBH5 in MM cells increased SAV1 m6A levels, decreased SAV1 mRNA stability and expression, suppressed the stem cell related HIPPO-pathway signalling and ultimately activates the downstream effector YAP, exerting an anti-myeloma effect." (PMID 35414790, 2022). "Taken together, ALKBH5 inhibition could increase SAV1 m6A levels, suppressed the HIPPO signalling pathway and ultimately activates the transcription factor YAP in myeloma cells, promoted the expression of P21, PUMA and BAX, exerting an anti-myeloma effect in vivo and in vitro." (PMID 35414790, 2022). "Therefore, in this study, we only demonstrated that ALKBH5 increased the percentage of SP cells and CD138-/CD34- myeloma stem cells by activating cancer stem cell related HIPPO pathway signalling and promoting the expression of pluripotency factors NANOG, SOX2 and OCT4." (PMID 35414790, 2022). "Both in vitro and in vivo studies revealed that ALKBH5-demethylated lncRNA SNHG15 regulates malignant phenotypes of MM, including viability and migration/invasion of MM cells, implying it is a novel and critical myeloma-promoting molecule and might be a potential therapeutic target of MM." (PMID 38145297, 2024).
atherosclerosis (5 papers, 2022 to 2026). A disease characterized by the build-up of fatty material and calcium deposition in the arterial wall resulting in partial or complete occlusion of the arterial lumen. "Our results showed that ox-LDL and IL-1β stimulation upregulated ALKBH5 in HCAECs, suggesting a role for this factor in regulating ECs function and angiogenesis in atherosclerosis." (PMID 40225569, 2025). "Overall, ALKBH5 may play a regulatory role in activating EC phenotype, worsening disease progression by promoting angiogenesis, cell migration and adhesion in atherosclerosis." (PMID 40225569, 2025). "In vitro experiments were conducted to further investigate the effects of ALKBH5, WTAP and METTL3 on atherosclerosis." (PMID 40225569, 2025). "The experimental results demonstrated the roles of ALKBH5, WTAP and METTL3 in atherosclerotic processes, which are consistent with recent studies on m6A in atherosclerosis." (PMID 40225569, 2025). "Developing inhibitors or agonists for key molecules such as NLRP3 inflammasome, ALKBH5, MTHFD2, or specific immunoproteasome subunits could lead to novel immune-based strategies for atherosclerosis, offering more precise and effective clinical treatments." (PMID 41562048, 2025).